DNAH11 (dynein axonemal heavy chain 11)
Diseases named in the same sentence as DNAH11 in open-access papers (continued):
Sharing a sentence is not in itself a finding about the gene and the disease.
Sepsis (2 papers, 2020 to 2023). Sepsis is defined as life-threatening organ dysfunction caused by a dysregulated host response to infection. "At the genetic level, seven susceptibility genes for sepsis in severe burn patients were found: DNAH11, LAMA2, ABCA2, ZFAND4, CEP290, MUC20 and ENTPD1." (PMID 36659877, 2023). "have found that the plasma peptide DNAH11 is strongly associated with sepsis." (PMID 36659877, 2023). "In the present study, mutations in ENTPD1, ZFAND4, DNAH11 and LAMA2 increased the risk of comorbid sepsis in severely burned patients." (PMID 36659877, 2023). "Through genomic analysis, we identified seven important susceptibility genes (DNAH11, LAMA2, ABCA2, ZFAND4, CEP290, MUC20 and ENTPD1) in patients with severe burn injuries complicated with sepsis." (PMID 36659877, 2023). "The DNAH11, ZFAND4, LAMA2 and ENTPD1 genes have been shown to have protective effects against sepsis." (PMID 36659877, 2023).
esophageal squamous cell carcinoma (1 paper, 2019). Esophageal squamous cell carcinoma (ESCC) is a type of esophageal carcinoma (EC) that can affect any part of the esophagus, but is usually located in the upper or middle third. "Until now, evidences have confirmed the association of the polymorphism rs2285947 in DNAH11 with the higher risk of human cancers, such as ovarian cancer, head and neck cancer, lung cancer, non-cardia gastric cancer and esophageal squamous cell carcinoma." (PMID 31053115, 2019). "A recent GWAS has discovered three novel intronic single nucleotide polymorphisms in genes LRFN2 (rs2494938), DNAH11 (rs2285947) and PLCXD2 (rs2399395) that are associated with altered risk of esophageal squamous cell carcinoma (ESCC) among Han Chinese populations." (PMID 31053115, 2019).
Fanconi anemia (1 paper, 2022). Fanconi anemia (FA) is a hereditary DNA repair disorder characterized by progressive pancytopenia with bone marrow failure, variable congenital malformations and predisposition to develop hematological or solid tumors. "Of note, these variants were associated with recessive inheritance for Fanconi anemia, complementation group C (FANCC), primary ciliary dyskinesis 7 (DNAH11), and primary ciliary dyskinesis 28 (SPAG1) so far." (PMID 35877578, 2022). "Three variants in immune genes were categorized in ClinVar as (L)P in association with the AR inheritance mode for Fanconi anemia, complementation group C (FANCC), primary ciliary dyskinesis 7 (DNAH11), and primary ciliary dyskinesis 28 (SPAG1)." (PMID 35877578, 2022).
hearing loss (1 paper, 2025). "Other individuals with DNAH11-negative staining included two individuals with hearing loss; HSVM analysis in one of them showed a stiff beating pattern, aligning with the previous studies." (PMID 40142748, 2025).
muscular dystrophy (1 paper, 2025). Muscular dystrophy (MD) refers to a group of more than 30 genetic diseases characterized by progressive weakness and degeneration of the skeletal muscles that control movement. "Another gene fusion involved the SGCD (Sarcoglycan Delta) and DNAH11 (Dynein Axonemal Heavy Chain 11) genes; SGCD is associated with muscular dystrophy, which could determine vascular malformations." (PMID 40904803, 2025).
pulmonary stenosis (1 paper, 2021). "The DNAH11 c.3426-1G>A variant in the homozygous state was previously identified in a fetus with structural abnormalities, including single atrium and ventricle, pulmonary stenosis, and right isomerism." (PMID 34133440, 2021).
retinal diseases (1 paper, 2023). "In particular, two breathing-relatedproteins (DNAH5 and DNAH11) appear of interest because mutations ofthe genes encoding these two proteins are involved with some ciliopathiesof the respiratory tract and with retinal diseases." (PMID 37552208, 2023).
Situs inversus totalis (1 paper, 2022). "Dynein axonemal heavy chain 17 (DNAH17) is a protein of the DNAH family of which four genes have already been associated with autosomal recessive PCD, situs inversus totalis or heterotaxy, namely DNAH1, DNAH5, DNAH9, and DNAH11." (PMID 35474353, 2022).
Waardenburg syndrome (1 paper, 2022). A disorder characterized by varying degrees of deafness and minor defects in structures arising from neural crest, including pigmentation anomalies of eyes, hair, and skin. "Six new genes were associated with NSHI: INPP4B, CCDC141, MYO19, DNAH11, SOX9, and POTEI; and one new gene, PAX8, was associated with Waardenburg syndrome." (PMID 35440622, 2022).
tumor (11 papers, 2018 to 2023). "The second discrepancy is a c.10654G>T substitution in DNAH11 with 17% VAF in the tumor tissue that was missed by both rounds of ctDNA WES." (PMID 37878600, 2023). "Tumor subtype analyses of LoF variants revealed evidence of association for ZFAND1, TYRO3, DNAH11, and PARP2 with ER-negative breast cancer, with ZFAND1 showing the strongest association (OR = 2.96 (CI 95% 1.59–5.50), p-value = 6.37 × 10−4)." (PMID 35884425, 2022). "It is notable that HLALOH occurred in the samples with recurrent mutations of S-C clonal pattern including KRAS, SYNE1, FBXL2, DNAH11 and CACNA1H, indicating this mutational clonal patter is facilitating tumor cell to escape immune monitor." (PMID 34453042, 2021). "Fisher’s exact test revealed that somatic mutations in CSPG4, DNAH11, INADL and TMPRSS13 were significantly associated with PD-L1-positive expression in RCC tumor cells." (PMID 30349421, 2018). "Moreover, our study revealed that 4 somatically mutated genes, including CSPG4, DNAH11, INADL and TMPRSS13, might act as promising predictive factors of PD-L1-positive expression in RCC tumor cells." (PMID 30349421, 2018). "Moreover, 4 somatically mutated genes, including CSPG4, DNAH11, INADL and TMPRSS13, might be promising predictive factors of PD-L1-positive expression in RCC tumor cells." (PMID 30349421, 2018). "SPP1, CRYAB, NNMT and HILPDA were highly expressed in tumour cells (ccRCC1); GSTA2, BHMT and ADSSL1 were highly expressed in tumour cells 1 (ccRCC2); and HIF1A-AS2, DNAH11 and EGOT were highly differentially expressed in tumour cells 2 (ccRCC2)." (PMID 34168986, 2021). "However, the genes such as KMT2D, DNAH11, and BRAF, which have a positive correlation with tumor immunity level, also up-regulated several immune-related miRNAs." (PMID 34211853, 2021). "In this study, among the 26 RCC cases, PD-L1-positive rate in tumor cells was significantly higher in specimens with 4 somatically mutated genes, including CSPG4, DNAH11, INADL and TMPRSS13, than in samples without those (P < 0.05)." (PMID 30349421, 2018). "Six genes were found to be altered in two tumours: MYO1A, DNAH11, SH2D5, ATM, MUC4 and ROS1." (PMID 29665859, 2018). "Among the 26 RCC cases, the PD-L1-positive rate in tumor cells was higher in samples with the 4 somatically mutated genes, including CSPG4, DNAH11, INADL and TMPRSS13, than in samples without those (P > 0.05)." (PMID 30349421, 2018).
cancer (8 papers, 2018 to 2024). A tumor composed of atypical neoplastic, often pleomorphic cells that invade other tissues. "In conclusion, a three‐generation family with three members affected by different types of cancer was found to have multiple germline predisposition genes, including DNAH11 and CFH." (PMID 38970307, 2024). "Similarly, the rs2285947 polymorphism in the DNAH11 gene has been linked to an increased risk of several cancer types, suggesting its potential contribution as a mini-driver gene in carcinogenesis." (PMID 37214090, 2023). "To further identify cancer‐predisposing SNVs, we screened COSMIC‐documented loci, leading to the identification of the SNVs DNAH11 c.9463G > A (p.Ala3155Thr) and CFH c.2314G > A (p.Asp772Asn) in the COSMIC database." (PMID 38970307, 2024). "Several genes with recurrent mutations were likely chance events, enhanced by their large size: DNAH11 (4516aa), TTN (34350aa), PIEZO1 (2521aa), TRPM6 (2022aa); none are thought to be involved in the pathogenesis of any form of cancer." (PMID 30256787, 2018). "Additional variants, including MUC5B, DNAH11, ANK2, and LAMA5, which were not part of tier-1 genes but has been reported in other gastrointestinal patients (according to the Cancer Browser) were also consistently detected." (PMID 37878600, 2023).
DNAH11 also shares sentences with these, for which no sentence is quoted: sinusitis (3 papers); infection (2); rhinitis (2); Azoospermia (1); bronchiolitis (1); bronchitis (1); calculus (1); CHARGE syndrome (1); cognitive decline (1); colon cancer (1); cone-rod dystrophies (1); cystic fibrosis (1); esophageal carcinoma (1); gastric cancer (1); glioma (1); Granuloma (1); head and neck cancer (1); hypogonadism (1); immune disease (1); Kartagener Syndrome (1); lung carcinoma (1); multiple myeloma (1); Neonatal respiratory distress (1); Noonan syndrome (1); oral diseases (1); ovarian carcinoma (1); pan (1); periodontal diseases (1); peroxisome biogenesis disorder 6A (1); pituitary tumor (1).
A further 3 diseases each share a sentence with DNAH11 in 1 paper.